CD4 (CD4 molecule)
Diseases named in the same sentence as CD4 in open-access papers (continued):
Sharing a sentence is not in itself a finding about the gene and the disease.
HIV-1 infection (continued). "Based on the rapid expansion and differentiation of Vδ1 T cells during HIV-1 infection, we investigated the dynamics of CD4 expression following activation in samples from HIV- donors." (PMID 39149467, 2024). "Acute HIV-1 infection depletes gut CD4 + T-cells and disrupts the intestinal epithelial barrier integrity, which, in turn, promotes microbial translocation into the systemic circulation." (PMID 39614246, 2024). "One of the primary challenges in curing HIV-1 infection is the persistence of proviral reservoirs in long-lived CD4+ T cells." (PMID 39373537, 2024). "We observed that HIV-1 infection leads to elevated levels of global DNA methylation in primary CD4 + T cells." (PMID 38671522, 2024). "Here, we investigated the regulatory role of NUP98 on HIV-1 as we observed a lowering of its endogenous levels upon HIV-1 infection in CD4+ T cells." (PMID 38449868, 2024). "Our data showed that infected siATG9-MoDC were two to three times more prone to transmit HIV-1 infection towards CD4+ T cells compared to HIV-1-R5-infected NT- and siCtrl-MoDC." (PMID 37240354, 2023). "During this stage, HIV-1 infects immune cells such as CD4+ T-cells or monocytes that traverse the blood-brain barrier, subsequently infecting microglia and disseminating HIV-1 infection in the CNS (101, –, 106)." (PMID 38032195, 2023). "There is nevertheless no cure for HIV-1 infection since HIV-1 persists in viral reservoirs of latently infected CD4+ T cells." (PMID 37936122, 2023). "In HIV-1 infection, cell-to-cell viral transmission at VS has been well documented and is mainly responsible for the high decrease in T CD4+ lymphocytes during the acute phase but especially during the AIDS phase of infection, thus having clinical importance." (PMID 37685911, 2023). "Given the permissiveness of activated CD4+ T cells to HIV-1 infection, one important source is the small surviving fraction of activated CD4+ T cells that return to rest and become long-lived memory cells following infection." (PMID 37632019, 2023). "LCs are antigen presenting cells that closely interact with HIV-1 target cells (i.e. CD4 T cells) after activation and migration to a lymph node in order to direct immune responses, making them ideal first target cells for HIV-1 infection." (PMID 36841916, 2023). "The first mathematical model for predicting the relationship between HIV-1 infection and stem cell therapy, comprises the interaction of four components, unaffected CD4+T-cells (T), infected CD4+T-cells (Ti), virus (V) and stem cells (S)." (PMID 37948418, 2023). "As a candidate, sphingolipid galactosylceramide (GalCer) has been reported to substitute for CD4 and promote HIV-1 infection in a CD4-independent mechanism." (PMID 37511488, 2023). "There was a case of a 43-year-old man with HIV-1 infection who had a CD4 count < 20 cells/μL and died following repeated seizures (suspected to have died from encephalitis)." (PMID 37657009, 2023). "CD4+ TSCM serve as a long-term viral reservoir for HIV type 1 (HIV-1) infection/latent infection, providing a stable host for HIV and functionally promoting long-term viral persistence in patients receiving highly active antiretroviral therapy." (PMID 36891319, 2023). "Some studies have shown that HIV-1–infected CD4+ T cells are characterized by increased glycolysis and glutaminolysis, which support HIV-1 infection." (PMID 37798121, 2023). "CD4 on exosomes derived from CD4+ T cells can reduce HIV-1 infection, while Nef in infected T cells can decrease CD4 expression in exosomes, effectively enhancing HIV-1 infection." (PMID 37063897, 2023). "The CD4+ T cell decline is defined as the number of CD4+ T cells depleted per year throughout the course of HIV-1 infection." (PMID 37161335, 2023). "During HIV-1 infection, a proportion of CD4+ TSCM exhibit increased sensitivity to HIV-1 infection by expressing the HIV core receptors CCR5 and CXCR4." (PMID 36891319, 2023).
HIV-1 infection (continued). "Once we confirmed the presence of HIV-1 infection within CD4+ T cells, we proceeded to evaluate their interactions with ML-NK cells." (PMID 37865647, 2023). "In fact, data show that the entry of glutamine-derived carbons into the mitochondrial tricarboxylic acid cycle (TCA) supports the early steps of HIV-1 infection in naïve and memory CD4 T-cells." (PMID 37446195, 2023). "A recent study has shown that human platelets endocytose HIV-1 during the acute phase of HIV-1 infection and can transmit the virus to CD4+ T-cells in resting and activated states through the formation of platelet-CD4+ T-cell complexes." (PMID 38257755, 2023). "Immune activation in ex vivo culture of immature mucosal sheets or direct activation of immature vaginal LCs by bacterial TLR ligands, including LPS, enhanced HIV-1 infection as well as transmission to CD4 T cells." (PMID 36841916, 2023). "Immune cells exhibiting reduced levels of CCR5, such as CD4+ T lymphocytes, tend to be more resistant to HIV-1 infection." (PMID 37766364, 2023). "On the contrary, a closer examination of all PD-1+IFN-γ+CD4+ cells (Th1 like cells) revealed that HIV-1 infection and exogenous spermidine induced FOXP3 expression in them." (PMID 36693889, 2023). "We used fluorescent HIV-1 reporters and confocal microscopy to evaluate the influence of HIV-1 infection and CD4+ T cells in NK cell response." (PMID 37865647, 2023). "We also identified that a small subset of naïve CD4+ T cell expressed CCR5, as well as activation and exhaustion markers interrogated, reflecting the potential for naïve CD4+ T cells to be permissive to HIV-1 infection." (PMID 37033916, 2023). "CD4+ T cell morphology is also disrupted during secondary immunodeficiencies like HIV-1 infection due to Nef-mediated cytoskeletal rearrangements." (PMID 37892982, 2023). "The study of CD4+ T cells has shown that HIV-1 infection is strongly impaired when glucose metabolism is inhibited." (PMID 37798121, 2023). "CD4 is the receptor molecule required for HIV-1 infection and CD4+ T cell count is considered an important component of HIV disease management and the gold standard for assessing disease progression." (PMID 37063897, 2023). "The CD4-binding site (CD4-bs) is a conserved region on the HIV-1 gp120 that is crucial for the CD4-gp120 interaction required for successful HIV-1 infection." (PMID 36677538, 2023). "Renal PedThy mice had similar immune reconstitution in the blood, spleen and intestine as BLT mice, while Leg PedThy mice had transient detection of immune cells, particularly CD4+ T cells and macrophages, the target cells for HIV-1 infection." (PMID 37816950, 2023). "We reported that upon HIV-1 infection of the CD4+ T-lymphocytes, there occurs a secretion of specific microRNAs from these infected cells in a differential manner with miR-15a and miR-24 regulated down and up, respectively." (PMID 38155835, 2023). "The results were obtained using the tanh-expansion method of HIV-1 infection with a mathematical model of CD4+ T- cells." (PMID 37948418, 2023). "Persistence of a latent reservoir in resting CD4+ T cells is the major barrier to curing HIV-1 infection." (PMID 37844236, 2023). "In the present study, we aimed to understand the role of IL-15 in the survival and proliferation CCR5+CD4+ T cells prior to and during HIV-1 infection." (PMID 36821374, 2023). "As CD4+ T cells are targets of HIV-1 infection, these cells are important in a model to study infection or transmission." (PMID 37816950, 2023). "This includes resting memory CD4+ T cells with integrated virus genome in individuals in the later stage of HIV-1 infection." (PMID 36672230, 2023). "HIV-1 infection is characterized by the depletion of CD4+ T cells and the main immune driver of control of infection is CD8+ T cells." (PMID 37267224, 2023).
HIV-1 infection (continued). "After activation and HIV-1 infection of purified autologous CD4+ T cells, these cells were co-cultured with autologous NK cells in an effector-target ratio of 1:4." (PMID 37798386, 2023). "To address if HIV-1 infection resulted in functional activation of individual caspases, we stained the infected CD4 T cells with individual FLICA probes for members of initiator, inflammatory and executioner classes of caspases." (PMID 36780482, 2023). "Although metabolic plasticity mediated by autophagy in the form of recycled glutamine is key to ensure optimal HIV-1-specific CD4 T-cell responses, it is also involved in polyclonal T-cell activation which generates new targets for HIV-1 infection." (PMID 37446195, 2023). "In HIV-1-infected BLT mice fed PDDC-containing chow, CD14+ and CD4+ cell numbers were reduced below the levels observed with untreated HIV-1 infection." (PMID 37406092, 2023). "We also found that a high CD4 count played a key role in inclusion in the network, as opposite to its protective role in HIV-1 infection immunity." (PMID 38125421, 2023). "An untreated HIV-1 infection is characterized by an increase in CD8 cells, which is associated with the viral load level, and a decrease in CD4 target cells." (PMID 37887742, 2023). "In the context of HIV infection, Palmer and co-workers have revealed that CD4+ T cells activated by HIV-1 infection switch metabolic phenotype from oxidative metabolism to aerobic glycolysis." (PMID 37798121, 2023). "The HIV-1 inhibitory effects of asparagine-conjugated (COS-N) and glutamine-conjugated (COS-Q) COS were evaluated by their ability to protect C8166 CD4+ human T cell lines from HIV-1 infection and infection-mediated death." (PMID 36810445, 2023). "Treatment with either harmine or Epivir/Kaletra reduced the frequency of HIV-1 infection in CD4+ T cells reflecting an inhibition of the virus expansion within the culture." (PMID 37706687, 2023). "HIV-1 infection has been shown to interfere with mTOR signaling, which usually results in diminished mTOR expression levels in immune cells, particularly in CD4+ T cells." (PMID 36992700, 2023). "The persistence of latent, replication-competent HIV-1 proviruses in resting CD4+ T cells represents a major barrier to curing HIV-1 infection." (PMID 36671485, 2023). "While ARVs preserved CD4+ cell numbers, PDDC reduced CD14+ and CD4+ cell numbers to below those observed with untreated HIV-1 infection." (PMID 37406092, 2023). "HIV-1 utilizes metabolically active cellular environments for establishing productive and latent HIV-1 infection in CD4+ T cells." (PMID 37662898, 2023). "We confirmed that HIV-1 infection significantly induced NLRP3 in HTOC CD4+ T cells expanding in the presence of ARI." (PMID 36693889, 2023). "In the 7 participants with subtype B HIV-1 infection, the median intact proviral DNA load was 7.96 copies per million CD4+ T cells." (PMID 37033916, 2023). "HIV-1 infection is initiated by binding of the viral envelope glycoprotein (Env), a trimer consisting of the gp120 and gp41 subunits, to CD4 on CD4+ T cells, facilitated by cellular coreceptors (e.g., CXCR4 or CCR5) to trigger membrane fusion." (PMID 36541800, 2023). "Infected cells were found most prominently in the CD4+ T cell compartment, consistent with the understanding that CD4+ T cells are most permissive to HIV-1 infection." (PMID 37325659, 2023). "Although iDCs express receptors and co-receptors required for HIV-1 infection, their infection rates in culture are lower than the ones for activated CD4+ T cells or macrophages." (PMID 36940134, 2023). "Strikingly, bacterial ligands and activation of vaginal LCs increased HIV-1 infection and subsequent transmission to CD4 T cells." (PMID 36841916, 2023). "We chose SupT1 cells for generating these stable cell lines, since SupT1 cells are characterized by high CD4+ expression on the cell surface; this feature increases the efficiency of HIV-1 infection." (PMID 37933844, 2023).
HIV-1 infection (continued). "These young MSM exhibited a higher median CD4 count, a higher proportion of CD4hi cases, and a higher rate of recent HIV-1 infection than cases aged 30 years and more." (PMID 36504809, 2022). "During ART, the peripheral CD4+ T cell counts in individuals with chronic HIV-1 infection represent an important immune parameter for host immune restoration." (PMID 35351857, 2022). "We propose that MΦ infection through viral transfer from infected CD4+ T cells impacts different aspects of the pathophysiology of HIV-1 infection, renewing our understanding of the role of MΦ in HIV-1 pathogenesis and persistence." (PMID 35622876, 2022). "We next compared the efficiencies of MT-C34 peptide delivery, the levels of MT-C34 cell surface expression, and the degree of CD4 lymphocyte protection from HIV-1 infection using the CRISPR/Cas9-based KI and a standard lentiviral vector (LV) transduction." (PMID 35073736, 2022). "For instance, CCR5 gene-edited primary human CD4+ T cells were found to be resistant to HIV-1 infection in vitro, recapitulating results obtained with other gene editing tools, such as TALENs and zinc finger nucleases." (PMID 35892930, 2022). "We have recently demonstrated that inhibition of S1P receptors with the functional antagonist FTY720 (fingolimod/gilenya) inhibits HIV-1 infection of primary CD4 T cells by multiple mechanisms." (PMID 35412343, 2022). "CD4+ T cells were first quantified in samples from three groups: uninfected individuals (healthy controls, HC, n=21), individuals with acute-phase HIV-1 infection (AHI, n=25) and matched individuals with chronic-phase infection (CHI, n=25)." (PMID 35222430, 2022). "In VNPs, the lack of viral pathogenesis has been associated with the preservation of central memory and stem-cell memory CD4+ T cells through reduced HIV-1 infection and maintenance of proliferative capacity." (PMID 34668779, 2022). "Previous reports have demonstrated expression of CXCR4 on astrocytes and neurons; however, this observation appears to have little relevance to HIV-1 infection given that these cells lack CD4." (PMID 35975998, 2022). "We also observed a similar result that the negative association trends between the frequency of IL-21+ICOS+cTfh cells and CD4+T cell count in both acute and chronic HIV-1 infection stage." (PMID 35222430, 2022). "This study for the first time presents SS-SBT-based four-digit typing data on HLA-A, -B, and -C alleles in Ghana, describing impact of HLA on viral load and CD4 count in HIV-1 infection." (PMID 35653364, 2022). "It is well documented that during the initial phase of HIV-1 infection there is a massive depletion of gut-resident CD4 T-cells in HIV-1 and SIV infections." (PMID 35633761, 2022). "Immune activation during HIV-1 infection is not limited to the target CD4+ T cells but engages a range of molecular and cellular processes in both the innate and adaptive arms of the immune system." (PMID 36175869, 2022). "By analogy, in HIV-1 infection the massive depletion of proliferative cells such as Tregs would render CD4 T-cell proliferation out of control." (PMID 35633761, 2022). "Comparison analyses on the median ages, CD4 counts, proportions of stratified age groups and CD4 count groups, and rates of recent HIV-1 infection among different population and sampling times were performed to understand temporal HIV-1 epidemic features." (PMID 36504809, 2022). "We then determined that CD98high CD4+ T cells were highly permissive for HIV-1 infection compared to CD98low CD4+ T cells." (PMID 36214569, 2022). "Here we have shown that HIV-1 infection of resting memory CD4+ T cells in vitro induces T cells to differentiate and gain characteristics that align closely with a phenotypic and transcriptional program of TRM T cells." (PMID 35417711, 2022). "Infected macrophages promote CD4+ T cell death, but before their demise, T cells spread HIV-1 infection to other T cells." (PMID 35203323, 2022).
HIV-1 infection (continued). "A recent study found that resveratrol significantly reduced HIV-1 infection in CD4 T cells by cutting off the production of reverse transcripts." (PMID 36389792, 2022). "As such, is it possible that TRAIL plays a role in the depletion of CD4+ T-cells during HIV-1 infection?" (PMID 35185920, 2022). "Here, we assessed TDP-43 activity in terms of regulating CD4+ T-cell permissivity to HIV-1 infection." (PMID 35682862, 2022). "A 28-year-old man was diagnosed with HIV-1 infection (CD4+ count: 3 cells/μL nd 563000 HIV-1 RNA copies/mL) and simultaneous Pneumocystis jirovecii pneumonia, disseminated Mycobacterium avium complex infection and SARS-CoV-2 infection." (PMID 35056592, 2022). "HIV-1 infection of the human CD4 + T cells triggers a massive increase in m6A in both host and viral mRNAs." (PMID 36085064, 2022). "Although we have recently shed light on the involvement of S1PR in HIV-1 infection in CD4 T cells, to our knowledge this is the first investigation into the role of SPHKs in HIV-1 infection." (PMID 35412343, 2022). "HIV-1 infection produces a long-lived reservoir of latently infected CD4+ T cells that represents the major barrier to HIV-1 cure." (PMID 35042816, 2022). "Decreased viral load, in turn, lessons damage to the immune system, such as CD4 count, which is depleted by HIV-1 infection." (PMID 35453518, 2022). "We also investigated the relationship between cTfh cells and CD4+T cell count or plasma HIV-1 viral load after HIV-1 infection." (PMID 35222430, 2022). "Previous studies have suggested that apoptosis is the main driver of CD4 T cell death during HIV-1 infection using ex vivo models." (PMID 36000842, 2022). "Although primary CD4 T cells represent a more relevant model for HIV-1 infection, these cells are very difficult to grow and infect, and they are rapidly killed by the virus, rendering any biochemical analyses technically challenging." (PMID 35163318, 2022). "The data show that as plasma viral load increases in the mice, CD4+ T cells decrease over time, which accurately models HIV-1 infection in humans." (PMID 34818071, 2022). "Since IFN-I pre-treatment limited HIV-1 infection in WT primary human CD4+ T cells, and to a greater extent in ISG15KO cells, upregulation of a combination of differentially expressed genes is likely responsible for the HIV-1 resistance demonstrated here." (PMID 35333911, 2022). "LY6E was shown to differentially regulate HIV-1 infection depending on cell surface CD4 expression levels." (PMID 35333911, 2022). "Since CD4mc competes with CD4 expressed on target cells and thereby inhibits HIV-1 infection, we used Cf2/CCR5 cells expressing the cognate coreceptor for JRFL Env but lacking CD4." (PMID 35891369, 2022). "Taken together, the results suggested that CMI02 and CMI06 can efficiently modify human primary CD4+ T cells with high resistance to HIV-1 infection and survival advantage." (PMID 34821542, 2022). "Decreased conversion of sphingosine to S1P via SPHK inhibition supports our model of S1P promoting HIV-1 infection in CD4 T cells, which our previous work indicates." (PMID 35412343, 2022). "We previously analyzed the relationship between gut CD4+ T cell immunity and dysbiosis during untreated, chronic HIV-1 infection." (PMID 35938870, 2022). "On day 14 after HIV-1 infection CD4:CD8 ratios were significantly lower upon NK cell depletion compared with non-NK cell depleted mice, wit the exception of the LNs." (PMID 36282589, 2022). "Taken together, our results demonstrated that GPI-10E8 conferred strong selective survival and expansion advantages to human CD4+ T cells following HIV-1 infection." (PMID 34821542, 2022). "This new work showed that glutamine fuels mitochondrial-related metabolic processes such as the TCA cycle and OxPhos, providing optimal HIV-1 infection in activated naïve and memory CD4+ T cells." (PMID 35205318, 2022).